ENSG00000237378 (novel keratin-associated protein)
Synonyms: LOC112267897
Gene: Protein-coding gene on chromosome 13 (63,746,741 to 63,751,080, forward strand). Ensembl gene ENSG00000237378.
Gene Ontology:
Biological process: hair follicle development
Genetic constraint (gnomAD): Loss-of-function variants: 2 observed, 3.88 expected, observed/expected ratio (o/e) 0.51, 90% interval 0.21 to 1.52. That is too few expected variants to judge how well the gene tolerates losing a copy. Missense variants: 62 observed, 55.93 expected, observed/expected ratio (o/e) 1.11, 90% interval 0.9 to 1.37. Synonymous variants: 16 observed, 19.87 expected, observed/expected ratio (o/e) 0.81, 90% interval 0.54 to 1.22.